IFNG (interferon gamma)
Diseases named in the same sentence as IFNG in open-access papers (continued):
Sharing a sentence is not in itself a finding about the gene and the disease.
infection (continued). "Upon infection, glucocorticoids (GC), inflammatory cytokines, e.g. Ifnγ, etc are induced, which enhance thymocyte death." (PMID 28091621, 2017). "Studies with Ifnγ−/− mice demonstrated that endogenous Ifnγ produced during infection enhances the depletion of DN2-DN4 subsets, promotes the accumulation of DP3 and delays the maturation of SP thymocytes." (PMID 28091621, 2017). "As a result, the observed lower levels of IFNγ in vaccinated mice after infection with B. pseudomallei are most probably a reflection of a decreased inflammatory state." (PMID 28323523, 2017). "IL-17A promotes IFNγ-induced expression of iNOS and NO release in lung epithelial cells in vivo and acts protective in the infection with C. muridarum." (PMID 28222146, 2017). "Treatment of immunocompetent or immunodeficient mice with exogenous IL-12 prior to infection with C. parvum reduced the severity of infection in an IFNγ dependent manner." (PMID 28800747, 2017). "In the self‐resolutive Pcc model, six of 10 peptides tested elicited IFNγ/TNF‐producing CD4 responses at day 6 post‐infection (Fig EV2B)." (PMID 28935714, 2017). "Blocking of IL-4 at the infection site impaired IFNγ secretion by dLN T cells 7 days later and increased IL-4 secretion by dLN cells 1 week post infection." (PMID 29067025, 2017). "Unlike Chlamydia, stimulation of Ms- and Ec-infected macrophages with IFNγ enhanced the infection induced levels of NO synergistically at both 24 h and 48 h post infection, confirming Chlamydia-driven interference of macrophages." (PMID 29375545, 2017). "In human VL, there is a strong Th1 cytokine response (IFNγ, IL-1, IL-6, IL-12 and TNFα) at the site of infection, but this is inexplicably unable to control the infection." (PMID 28103263, 2017). "Methods for testing other cell markers of immune activity than antibody response, for example, interferon gamma production would also be desirable to distinguish immunity from ongoing infection." (PMID 29318041, 2017). "Four weeks after infection, the frequency of IFNγ and IL-4 producing cells was analyzed by flow cytometry at the site of infection." (PMID 29067025, 2017). "A modest but significant rescue in the total number of thymocytes post 4 days of infection was observed in Ifnγ−/− mice, as compared to BL/6 mice." (PMID 28091621, 2017). "Administration of IFNγ was shown to have the potential to augment the host response to control infection against A. fumigatus in immunocompromised individuals and CGD patients, improving outcome and reducing mortality." (PMID 29371571, 2017). "The same was true at day 4 post‐infection (Fig EV4B) indicating that cDC1 are not only important for maintenance of IFNγ+ TNF+ Th1 cells but also for their priming." (PMID 28935714, 2017). "Deficiency of CD4+ T cells would thus be expected to result in reduced IFNγ production and impaired ability of the host to control infection." (PMID 28493863, 2017). "In line with the elevated levels of IFNγ detected at the site of infection and in dLN cells, high levels of serum IgG2c were observed in KRT14CreIL-4Rα−/lox and control IL-4Rα−/lox mice." (PMID 29067025, 2017). "In our cohort, both IFNγ/IL10 coproducing and IL10 single-producing subsets were associated parasite density during recent infection, while only IL10 single-producing responses were associated with protection from symptomatic disease." (PMID 29097996, 2017). "These cells were infected with C. trachomatis, stimulated with interferon gamma (IFNγ), fixed at 14 hours post infection (hpi) and subsequently stained." (PMID 28945814, 2017). "At this late point in time IFNγ expression was significantly enhanced and IFNγ-producing CD8+ T cells reached frequencies (19.93±0.52%) comparable to those observed on day 7 post infection." (PMID 28222146, 2017).
infection (continued). "First, to ensure that digestion of the ear would not impact IL-4 detection, KN2/4get mice, all on the C57BL/6 genetic background, were treated with anti-IFNγ and anti-IL-12 mAbs at the onset of infection to induce Th2 cell differentiation." (PMID 29067025, 2017). "The level of serum cytokine interferon gamma following oral administration of the L16 strain was remarkably increased during infection, as were interleukin-4 levels during convalescence." (PMID 28577529, 2017). "Substantial numbers were also found in the spleens of naïve mice 5 days after influenza virus challenge, indicating induction of IFNγ-producing cells by the infection." (PMID 28749414, 2017). "Cluster 3 was highly enriched for Th1/2 cell differentiation, IFNγ, IL-12, CD8, and NK cell signaling pathways and was strongly associated with infection and age and marginally associated with sex, but interestingly not with TP or TF." (PMID 28966918, 2017). "We thus investigated by transmission electron microscopy the integrity of the vacuolar membrane of type II Toxoplasma in IFNγ-stimulated wild-type or TRIM21 knockout MEFs 2 h after infection." (PMID 28701773, 2017). "In vitro, IFNγ fuels astrocyte infection by T. cruzi, and IFNγ-stimulated infected astrocytes are implicated as potential sources of tumor necrosis factor (TNF)." (PMID 28877735, 2017). "After infection, the highest percentage of detection of infected deer with the IFNγ assay was for bPPD at the initial stage of the disease (92.8 to 100%) in comparison with other antigens, which is again in parallel with previous reports for ruminants." (PMID 29145844, 2017). "The increase in TNFα and IFNγ mRNA in the neonatal lungs after MRSA infection demonstrate that neonates are capable of inducing a pro-inflammatory response following infection." (PMID 28060871, 2017). "We therefore exposed MDM to IFNγ prior to infection and examined their response to internalized aggregates of Mtb." (PMID 28130921, 2017). "R. conorii-infected C3H/HeN mice produced enhanced serum levels of IFNγ and IL-12, the main IFNγ-inducing factor for T cells and NK cells, in the first days of infection." (PMID 28222146, 2017). "Strikingly, αDEC-205/OVA vaccination resulted in an exceptionally strong accumulation of IFNγ-producing CD44highCD8+ effector memory T cells (27.6%) in the liver following AdOVA-GFP-luc infection." (PMID 28266658, 2017). "Strikingly, neonatal CD8+ cells in the mesenteric lymph nodes (MLN) are rapidly mobilized, increasing in proportion, number, and IFNγ production as early as 48 h post infection." (PMID 28119902, 2016). "IFNG has been reported as an important feature of innate and adaptive immunity and is specified by the quick response and increased production against an infection." (PMID 27733800, 2016). "With the absence or reduction of these regulatory pathways early in infection, late stage increases in IFNγ occur serving as a marker of inflammation." (PMID 27936058, 2016). "Taken together, our results suggest mild-inflammation in early stage infection characterised by upregulation of circulating interferon-gamma production in newly infected TB patients." (PMID 26880909, 2016). "A complete absence of specific antibodies was observed both for the five WT and five IFNγ-/- mice after 5 and 8 weeks of infection." (PMID 26863011, 2016). "Several lines of evidence support a direct role for IFNγ in impacting murine progenitor cells in the context of infection." (PMID 27621733, 2016). "While low cell recovery in 35A infected animals prevented us from adequately assessing the IFNγ response at day 8, we found significantly fewer IFNγ + P14 T cells in 35A infected mice at day 4 post infection." (PMID 26915099, 2016). "Firstly, B cell-deficient μMT mice that had resolved infection were challenged with HSV and transferred gDT-II T cells were examined for direct activation by measuring IFNγ production in an ex vivo cytokine secretion assay." (PMID 27160938, 2016).
infection (continued). "We chose 13 and 19 days post-infection, time points that flank the 14–15 day time point when IFNγ-producing T cells begin to arrive in the lung after aerosol Mtb infection." (PMID 27512905, 2016). "Pulmonary levels of IFNγ, IL-1α, IL-1β and CXCL1/KC were highly increased in TNFα-deficient mice one month after infection, when severe pathology develops, with a reduction of IL-12/23p40 and p19, in line with transcriptome data." (PMID 27853279, 2016). "The ratio of IFNγ+TNF+ (e.g., double producers) to total IFNγ producers fell as infection persisted." (PMID 26967901, 2016). "LPS and IFNγ treatment leads to M1 macrophage polarization, suited for combating infection and acute inflammation, whereas IL4 treatment leads to M2 polarization." (PMID 27006955, 2016). "Together with the observed presence of less extracellular debris in IFNγ-/- mice during the early phase of the infection, this indicates that CMI is critical for host immunity against M. ulcerans infections." (PMID 26863011, 2016). "Thereafter, the expression of both of these cytokines waned dramatically, and within 48–60 hours of infection IFNγ and IFNα were undetectable within the plasma." (PMID 27580079, 2016). "We found strong support for an age-independent effect of bTB infection status on the IFNγ response, with ‘excretor’ classes having weaker IFNγ responses than both ‘negative’ and ‘positive’ classes." (PMID 26888036, 2016). "Generally, mice consuming the WB diets displayed lower expression of bacterial recognition genes (Tlr4, RegIIIγ), the defense cytokine gene Relmβ, the Th1 regulatory cytokine gene Ifnγ, and the regulatory cytokine gene Il-10 during peak and late infection." (PMID 28031748, 2016). "Eight weeks after infection the foot pads of the IFNγ-/- mice were still more oedematous and necrotic than those of the WT animals and the infection even affected the adjacent joints and legs (Fig 2A7–2A9 and 2B7–2B9)." (PMID 26863011, 2016). "As expected, at the site of infection, the levels of proinflammatory cytokines IL-12, IFNγ, and IL-17 were increased, and the level of immunoregulatory cytokine IL-10 was decreased, 5 days after infection with three T. gondii strains." (PMID 27721814, 2016). "Taken together, our data showed that IFNγ+IL10+ CD4+ T cells are present during the first-ever symptomatic infection with P. falciparum in naïve individuals as well as in individuals who were last exposed > 5 years ago." (PMID 27802341, 2016). "IL-6 and TNFα are critical for rapid response to tissue injury and infections and induce the production of acute phase reactants in the liver whereas IL-12 is the main inducer of IFNγ in NK cells and T cells." (PMID 27548618, 2016). "Culture supernatant was sampled at regular intervals between days 1 to 14 post-infection and the IFNγ concentration quantified by ELISA as a measure of T cell recognition." (PMID 27096949, 2016). "DNA methylation levels at the IFNG 5′ promoter were significantly lower in CD4+ T lymphocytes during infection with M. bovis." (PMID 27507428, 2016). "Infection with the attenuated type I strain cps1-1 induced an increase in both frequency and absolute number of IFNγ+ cNK cells." (PMID 27721814, 2016). "It is possible that IFNγ production by T-cells is required to afford protection to the NSPC pool at later time points in infection." (PMID 27178303, 2016). "In response to these three parasite strains, murine cNK cells produce IFNγ and become cytotoxic and polyfunctional (IFNγ+CD107a+) at the site of infection." (PMID 27721814, 2016). "We established the pattern of infection of U937 cells, which had been activated with interferon gamma (IFN-γ), by B. pseudomallei K96243 expressing red fluorescent protein (RFP)." (PMID 27484700, 2016). "Newly committed neuronal cells were lost at all time points post-infection in CD46+/IFNγ-KO pups and at 7 and 10 dpi in CD46+ pups." (PMID 27178303, 2016).
infection (continued). "Following DPV-enhanced green fluorescent protein (EGFP) infection of duck embryo fibroblast cells (DEFs) with IFNα and IFNγ pre-treatment, the number of viral gene copies decreased more than 100-fold, with viral titers dropping approximately 100-fold." (PMID 27438848, 2016). "Using a unique in vitro model, we showed that hrHPV infection renders KCs resistant to IFNγ/TNFα-induced necroptosis and arrest of cell growth." (PMID 27920775, 2016). "In response to infection, IFNγ upregulates a vast number of proteins, with a family of large GTPases, the Guanylate Binding Proteins (GBPs), being among the most highly induced." (PMID 26874079, 2016). "Intracellular cytokine staining paralleled these findings as infection of DCs with EBOV significantly reduced percentages of T cells positive for activation markers IFNγ, IL2 or TNFα, as well as for the marker of degranulation CD107α+." (PMID 27930745, 2016). "Although the difference in the foot pad thickness resolved after 8 weeks of infection, the infected feet of the IFNγ-/- animals were more inflamed and clearly more ravaged at this time point." (PMID 26863011, 2016). "Plasmodium-specific interferon-gamma (IFN- γ) responses in vitro are associated with both human experimental and natural infections." (PMID 27604988, 2016). "The protective effects appear to manifest early after infection since CD8+ cells in the MLN selectively increase within 24 h of infection and over 1⁄4 of the cells are producing IFNγ just 48 h post infection." (PMID 28119902, 2016). "During secondary LCMV infection, IFNα and IFNγ are transiently produced during the first 24 hours of infection." (PMID 27580079, 2016). "Significant (p≤ 0.05) upregulation of the IFNγ (~ 3.3 fold) was observed in transfected cells after infection compared to ~ 0.9 fold in untransfected macrophages." (PMID 27494323, 2016). "IFNγ-treated cells infected with Ad5-WT were analyzed by immunofluorescence at 113 days post-infection to examine viral early and late gene expression in individual cells." (PMID 26809031, 2016). "A peak of enhanced frequencies of IFNγ-producing CD4+ T cells was detectable on day 7 post infection." (PMID 27875529, 2016). "Mice consuming the RS diet also exhibited a trend towards elevated (P = 0.083) expression of Ifnγ during late infection, and increased (P = 0.043) expression of the defence cytokine, Relmβ at peak infection as compared to mice consuming the WB diet." (PMID 28031748, 2016). "Regarding the IFN response, IFNα gene expression levels were higher in bronchiolar areas at early stages post-infection (12 dpi), while IFNγ was highly expressed also at bronchiolar areas, but in later stages of infection (24 and 72 hpi)." (PMID 27825367, 2016). "The generation of antigen-specific Th1 responses before infection was verified by measuring IFNγ and IL-5 after incubation of spleen cells from cohorts of immunized mice with their relevant immunizing antigen (data not shown)." (PMID 27142329, 2016). "As before, significantly higher levels of IFNG mRNA were detected in response to live S. Typhimurium 2 h post infection and also at 3 h." (PMID 27000047, 2016). "Long-term LCMV immune mice (>6 weeks post primary LCMV-Arm) were rechallenged with LCMV, and plasma was collected prior to, and at the indicated times following, the secondary infection; IFNα and IFNγ levels were assessed via ELISA or multiplex assay." (PMID 27580079, 2016). "We observed lower IFNγ concentrations with significant differences at day 21 (p < 0.05) and day 28 (p < 0.01) post-infection in p55∆NS mice compared to WT mice." (PMID 27995986, 2016). "Flow cytometric analysis revealed that NSPCs were reduced in CD46+/IFNγ-KO mice at 3, 7, and 10 days post-infection (dpi), but were unaffected in CD46+ mice." (PMID 27178303, 2016). "In the present study we show that CD4+ T cells are sufficient to protect against R. typhi in the C57BL/6 RAG1-/- infection model by activating MΦ via IFNγ and other factors." (PMID 27875529, 2016).
infection (continued). "CD46+ and CD46+/IFNγ-KO pups were mock or MV-infected on postnatal day 2 (P2) and whole brains were harvested at 3, 7, or 10 days post-infection (dpi)." (PMID 27178303, 2016). "Using either AIV infected syngeneic Antigen Presenting Cells or whole inactivated virus as recall stimulation, IFNγ responses were detected in birds of both lines after infection." (PMID 27279280, 2016). "All infections induced a predominantly EM phenotype in IFNγ+ cells at 7 days post infection (dpi), but this response remained EM in both MCMV infections until 180 dpi, while it rapidly shifted to a CM phenotype in rVACV infection." (PMID 27977791, 2016). "Protected mice received an intranasal B. pertussis challenge 56 days after the primary infection (D0) and showed increased percentages of IFNγ- and IL-17A-producing Prn-specific CD4+ CD44+ T-cells on 10 days p.c. compared to the percentage in naive mice." (PMID 27711188, 2016). "Antigen-specific T-helper cells type 1 (Th1), migrating to the site of infection, secrete interferon-gamma (IFN-gamma), which is critical for the host defense against M. tuberculosis." (PMID 28082976, 2016). "The patient had high titer, neutralizing antibodies to IFNγ, and succumbed to overwhelming infection." (PMID 31557985, 2016). "Three dpi corresponds to the initial phase of infection when the innate immune response predominates, including infiltration of IFNγ-producing natural killer (NK) cells." (PMID 27178303, 2016). "Conventional natural killer cells provide protection against infection and cancer by producing IFNγ and cytolytic activity." (PMID 27721814, 2016). "The increased IFNγ secretion at d3 post PbA infection by CD3+ T cells was confirmed in mice in which IL-22 was transiently neutralized compared to the control group." (PMID 27311945, 2016). "Here we have re-evaluated the role of IFNγ for host immune defense against M. ulcerans by comparing progression of the infection in IFNγ knockout and wild-type mice experimentally challenged with a fully virulent M. ulcerans isolate." (PMID 26863011, 2016). "Compared with naive animals, the level of IFNγ, IL-1β, IL-17A, and IL-12 was increased at 5 days post infection in PEC." (PMID 27721814, 2016). "In ehrlichiosis, HSC loss requires IFNγ sensing by macrophages, demonstrating that interferon signaling reduces the HSC supportive capacity of niche cells during infection-induced BM suppression." (PMID 27621733, 2016). "The induction of Ido1 and Ido2 transcripts by IFNγ within OHSCs mimics the cytokine-mediated response of the brain to a peripheral infection." (PMID 27142940, 2016). "Memory T cells that produced IFNγ appeared to be circulating effector/memory T cells that infiltrated the lung after infection." (PMID 27300652, 2016). "The concentration of IFNγ in rZJ1*L/IFNγ-infected allantoic fluids (AFs) increased over time until reaching peak concentrations between 72 and 96 hrs post-infection that saturated the ELISA." (PMID 27409587, 2016). "In vivo, IFNα and IFNγ were not upregulated in the brain after GPV infection, although interferon genes were differentially regulated in all tested tissues but showed an upward trend, and the IFNγ response was fairly strong after infection." (PMID 27150912, 2016). "Perforin-deficient mice, which globally lack cytotoxicity, survive avirulent parasite infection, likely because of intact IFNγ production." (PMID 26915066, 2016). "Although another study described a quite different immune response after intracardiac infection [mixed activating (IFNγ and TNFα)/deactivating (TGFβ) cytokine response], this route seems to be effective in term of infection persistence." (PMID 26969511, 2016). "Analysis of cell entry and interferon gamma release after infection with RSV reveals the importance of actin- and clathrin-dependent signaling in human immune cells." (PMID 27004689, 2016). "In the PEC, frequencies of IFNγ+ and cytotoxic (CD107a+) cNK cells increased 5 days after infection." (PMID 27721814, 2016).